PSEN1 (presenilin 1)
Diseases named in the same sentence as PSEN1 in open-access papers (continued):
Sharing a sentence is not in itself a finding about the gene and the disease.
Cognitive impairment (continued). "Our laboratory was the first (and we have continued to contribute data for the last 20 years) to show that PSEN1 expression is modulated by the methylation status of its 5′-flanking region and that its modulation affects amyloid deposition and cognitive impairment in TgCRND8 mice." (PMID 37511434, 2023). "To investigate whether F. mume mitigates cognitive impairments in AD, we used 5XFAD transgenic mice co-overexpressing human amyloid precursor protein (APP) and presenilin-1 (PS1) with five familial AD (FAD) mutations." (PMID 26852239, 2016). "Second, even though we only included human subjects with proven APP or PSEN1 mutations and no cognitive impairment, subjects may have been in different pre-symptomatic stages of the disease." (PMID 37608393, 2023). "Also, it is reported that the synthetic formula of AXT’ docosahexaenoic-acid-acylated AXT diesters (AXT-DHA) ameliorated cognitive disorders in mice with amyloid protein precursor/presenilin-1 (APP/PSEN1) by reducing chronic neuroinflammation and oxidative stress." (PMID 37179259, 2023). "On the one hand, segregation analyses of EOAD cases have been linked to mutations in the genes encoding APP, presenilin 1 (PSEN1), and PSEN2, which are involved in the main molecular mechanism of AD pathogenesis, triggering the cascade of amyloid-β deposition, resulting in cognitive impairments." (PMID 34968302, 2021). "3xTg-AD mice harbour three mutant genes for the beta-amyloid precursor protein (βAPPSwe), presenilin-1 (PS1M146V), and tauP301L; as a consequence, the mice progressively develop plaques and tangles, as well as cognitive impairments." (PMID 36901549, 2023). "This strain expresses mutant amyloid precursor protein (APPswe) and presenilin 1 (PS1∆E9), leading to overproduction of Aβ, which aggregates and accumulates into amyloid plaques from around 6 months of age, resulting in cognitive impairment." (PMID 36323689, 2022). "Here, we investigate the potentially protective effects of Xn on cognitive impairment in APP and presenilin 1 (PS1) double-transgenic mice, while screening key components of the gut microbiome via 16S rDNA sequencing." (PMID 35209070, 2022). "In APP/PSEN1 mice, PTEN-regulated cognitive impairment presents as increased synaptic long-term depression, which is ameliorated by inhibition of PTEN with VO-OHpic, or the synthetic peptide PTEN-PDZ, which disrupts the binding of PTEN to PSD-95." (PMID 32236736, 2020). "The aim of this study was to investigate the effect of EA on cognitive impairment and the role of the JNK signaling pathway in AD model amyloid precursor protein (APP)/presenilin 1 (PS1) mice." (PMID 32116652, 2020). "Therefore, this study aims to investigate the role of HIIT and CBD supplementation in ameliorating cognitive impairment in a rat model of Aꞵ-induced AD via targeting APOE, presenilin-1, and glutamate." (PMID 39539449, 2024). "Therefore, the present study raises the possibility that HIIT combined with CBD administration can alleviate cognitive impairment by regulating the expression of APOE, presenilin-1, and glutamate proteins in a rat model of AD induced by ꞵ-amyloid." (PMID 39539449, 2024). "In conclusion, combined with the results of the literature search and bioinformatic analysis, we believe that the three genes, BIRC6, TGFB1, and PSEN1, have a clear correlation with T2DM and cognitive impairment, which can be used as target genes for disease prediction in the future." (PMID 37189611, 2023). "In the similar context, treatment with Z-Phe-Ala-diazomethylketone (PADK; also known as ZFAD), a CTSB activator, reduced Aβ deposition and improved synaptic and cognitive dysfunctions in an APP/presenilin-1 (PS1) and mild cognitive impairment (MCI) mouse model." (PMID 34071457, 2021).
Cognitive impairment (continued). "Chinese hamster ovary cells (CHO) stably transfected with amyloid precursor protein (APP) and presenilin 1 (PS1) and SAMP8 mice fed with high-fat diets (HFDs, known to induce metabolic stress, leading to cognitive impairment and aging) have been used to mimic Alzheimer’s disease." (PMID 32260305, 2020). "The APP/PS1 mouse model is a double transgenic mouse model, expressing a chimeric mouse/human amyloid precursor protein, and a mutant human presenilin 1(PS1-dE9), and represents a model of familial AD with cognitive impairments, Aβ plaque deposition and synaptic abnormalities from 6 months of age." (PMID 31978506, 2020). "Recently, it was reported that mice lacking P2X7 have reduced Aβ load and cognitive impairment in another AD model overexpressing both human mutated APP and mutated presenilin-1 (APP–PSEN1)." (PMID 31507408, 2019). "Interestingly, the level of myostatin in 12-month-old double transgenic amyloid precursor protein and presenilin 1 (APP/PS1) mice was elevated, which may trigger skeletal muscle atrophy and cognitive deficits." (PMID 37577356, 2023). "Hereby, we study for the first time, using behavioural, transcriptomic and bioinformatic approaches, depressive-like symptoms in an AD mouse model (APP/PSEN1-Tg mice) at ages before the neuropathological features are manifest and when cognitive impairment is not yet evident." (PMID 33795014, 2021). "Therefore, AS-IV may improve cognitive impairment by binding to AD-related gene, such as caspase-1, TRPV1, PSEN1, and GSK3Β, reduce cell death, and ultimately inhibit AD-phenotypes." (PMID 34616501, 2021). "In the present study, we investigated whether EA treatment could ameliorate cognitive impairment and attenuate Aβ deposits, and the effect of EA treatment on BDNF expression and neurogenesis in the amyloid precursor protein (APP)/presenilin 1 (PS1) double transgenic (Tg) mice." (PMID 24447795, 2014). "Knocking out TREM1 in the brains of APP/PSEN1 mice has been shown to increase Aβ1–42 levels and total amyloid plaque burden, and selective overexpression or activation of TREM1 on microglia cells could improve Aβ neuropathology and rescue AD-related spatial cognitive impairments." (PMID 39626951, 2024). "We chose to use PS1-KI animals as control group as these mice overexpress mutant Presenilin-1 gene (M146V substitution) but, by lacking the expression of mutant APP and h-tau, do not show Aβ or tau-dependent pathology nor AD-related cognitive deficits." (PMID 21423579, 2011).
amyloid (60 papers, 2010 to 2026). "For instance, a homozygous carrier of the APOE ε3 Christchurch variant developed MCI nearly three decades later than expected, despite AD‐causative PSEN1 carriership and presence of amyloidosis." (PMID 40613482, 2025). "In 5xFAD mice, which express human APP and PSEN1 transgenes with five AD-linked mutations, leading to rapid development of amyloidosis, an increase in the phylum Firmicutes and a decrease in the phylum Bacteroidetes was observed at nine weeks." (PMID 33153085, 2020). "The APP/PSEN1 TG mice were behaviorally characterized in multiple studies demonstrating amyloidosis as early as 4–6 months, which was linked to behavioral decrements in spatial learning, including decrements in WM due to synaptic changes." (PMID 29186131, 2017). "APP/PSEN1 TG mice exhibit early amyloidosis as early as 4–6 months of age, reported to be associated with neuroinflammation and accumulation of cytokines." (PMID 29186131, 2017). "Transgenic mouse models carrying genetic mutations of amyloid protein precursor (APP) and presenilin-1 (PS1) are commonly used to assess the pharmacodynamics of potential amyloidosis-lowering and pro-cognitive compounds." (PMID 27421117, 2016). "PSAPP mice, expressing the “Swedish" amyloid precursor protein and M146L presenilin-1 mutations, are a well-characterized model for spontaneous amyloid plaque formation." (PMID 21607013, 2011). "This strain, which over-expresses both the 695 amino acid isoform of human amyloid precursor protein (APP) with K670N and M671L mutations and presenilin 1 with the A246E mutation, has accelerated amyloidosis and plaque formation." (PMID 20630068, 2010). "Similarly, the TgF344‐AD rat carrying mutations in APP and PSEN1 exhibits amyloid deposition, cognitive decline, and widespread neuronal apoptosis, making it a valuable model for studying late stages of AD." (PMID 40420360, 2025). "This inconsistency may be caused by the fact that PSEN-1 is involved in both amyloidosis and non-amyloidosis pathways of APP, and less is known about other pathophysiological functions of this protein." (PMID 36774494, 2023). "Taken together, the overall reduction in Aβ levels strongly suggest that other regulatory mechanisms or cellular components may exist and account for the strong amyloid pathology observed in AD patients carrying these FAD-linked PSEN1 mutations." (PMID 22529981, 2012). "Pioglitazone inhibits the amyloidogenic pathway, reducing BACE1, PSEN1, Aß42 levels and amyloid plaques, while increasing IDE and Pparg expression in PreDM and T2D models." (PMID 41146261, 2025). "Low-dose IL-2 treatment in the mid-stages of AD restores the Treg/Th17 balance, reduces neuroinflammation, and decreases amyloid plaque burden in APP/PS1 (Amyloid Precursor Protein/Presenilin-1) models, significantly improving cognition." (PMID 41357230, 2025). "5xFAD is an amyloid pathology model that expresses human APP and PSEN1 transgenes with a total of five AD-linked mutations." (PMID 33003412, 2020). "We previously concluded that deletion of Tyrobp can slow or delay the progression of learning deficits in APP/PSEN1 transgenic mice during the early stages of amyloid deposition." (PMID 30283032, 2019). "The selected model is an APP/(presenilin-1) PS1 double transgenic mouse that coexpresses five familial AD mutations (5XFAD) and exhibits an amyloid plaque pathology similar to that found in AD." (PMID 30684043, 2019). "To produce an AD mouse model that genetically lacks microglia, we crossed FIRE knockout mice with 5xfAD transgenic mice that harbor familial AD mutations in amyloid precursor protein (APP) and presenilin 1 (PSEN1) and develop robust parenchymal amyloid pathology." (PMID 35705056, 2022). "By contrast, AppNL-G-F/NL-G-F mice exhibit progressive amyloid pathology, including microglial and astrocytic activation and loss of synaptic markers, in the absence of Psen1 mutation." (PMID 30055565, 2018).
amyloid (continued). "Therefore, we can conclude that human microglia carrying either APP or PSEN1 ADAD mutations in isolation are not sufficient to cause amyloid pathology in the mouse brain." (PMID 38473822, 2024). "For example, it has been reported that, similar to CX3CR1 deficiency, amyloid precursor protein/presenilin-1 (APP/PS1) mice lacking CX3CL1 showed reduced amyloid pathology, and expression of obligate sFKN in this context did not improve or exacerbate this effect." (PMID 32410624, 2020). "PSEN1 mutations have been observed to associate with altered Ca2+ mitochondrial channels in the cerebellum, apparently causing reduced spike activity in Purkinje cells in the absence of amyloid plaque deposition." (PMID 29078805, 2017). "We investigated this cerebellar resistance using 5xFAD mice, an amyloidosis model with high expression of mutant human APP and PSEN1 in the cortex and cerebellum." (PMID 41597256, 2026). "MAPT, APP, PSEN1, and BACE1 are key proteins involved in the pathological hallmarks of AD, namely neurofibrillary tangles and amyloid plaques." (PMID 41195325, 2025). "As a first model of amyloidosis, we used transgenic mice expressing human amyloid precursor protein (APP) and presenilin 1 (PS1)." (PMID 29472246, 2018). "In double-transgenic amyloid precursor protein (APP)/presenilin 1 (PS1) murine models of AD, the role of DCs in amyloid plaque accumulation in the brain parenchyma is supported by evidence of increased formation of amyloid plaques following the systemic depletion of DCs." (PMID 32345316, 2020). "In contrast, PSEN1 KI mice lacking the APP are not known to develop amyloid pathology." (PMID 41496612, 2026).
cognitive decline (50 papers, 2013 to 2025). "A female sibling carrier of the RELN-COLBOS and PSEN1-E280A variants also presented with delayed age at onset of cognitive decline, although with less optimal protection compared to her brother and prolonged end-stage disease." (PMID 37188781, 2023). "Proband 3 (II:2) in family 3, carrying a duplication mutation (c.702_704dup and p.L235dup) in the PSEN1 gene, was a 45-year-old man who was admitted to our department because of a 2-year history of cognitive decline." (PMID 37051054, 2023). "Supporting for interventions that aim to modify or edit APOE comes from the recent report that homozygosis for the APOE3 Christchurch variant (R136S) markedly delayed cognitive decline in a single presenilin 1 (PSEN1) mutation carrier." (PMID 34289882, 2021). "Future research should focus on the determination of AMFE efficacy using relevant animal models, such as transgenic mice expressing human amyloid precursor protein and presenilin 1 mutations, to check its impact on AD-related neuropathology and cognitive decline." (PMID 40283926, 2025). "5xFAD mice contain three AD familial mutations in humanized APP and two in PSEN1, and exhibit Aβ plaques, neurodegeneration, and cognitive decline as they age." (PMID 38915309, 2024). "Though ADAD‐causing PSEN1 variants are highly penetrant, there is striking heterogeneity in the observed age of symptom onset, biomarker trajectories, and cognitive decline across individuals with different PSEN1 variants." (PMID 37291760, 2023). "Evidence shows that the APOEε4 allele influences autosomal dominant EOAD, because in patients with pathogenic variants of APP, the APOEε4 allele is associated with faster cognitive decline, whereas in carriers of pathogenic variants of PSEN1, an inverse effect is observed." (PMID 37958671, 2023). "In addition, we evaluated two FAD-causing PSEN1 variants (Y154N and T291P) where motor symptoms (spastic paraplegia, SP) precede cognitive decline by several years." (PMID 35365805, 2022). "Additionally, the possession of two copies of the APOE3 Christchurch variant (R136S) markedly delayed cognitive decline in a presenilin 1 (PSEN1) mutation carrier, likely by limiting tau accumulation in the brain." (PMID 33148290, 2020). "The carriers of PSEN1 mutation presented with isolated and progressive cognitive decline." (PMID 31557888, 2019). "Among carriers of the PSEN1 mutation, the clinical presentation was mainly isolated progressive cognitive decline, but six patients carrying either the p.(Pro264Leu), p.(Leu173Trp), p.(Gln222His), or the Δ9–10 PSEN1 mutation displayed an associated phenotype of spastic paraparesis." (PMID 28350801, 2017). "PSEN1 mutations might progressively impair neurogenesis, which is closely related to the memory deficits and cognitive decline in AD." (PMID 27926491, 2017). "Because the purpose of this endophenotype-based approach is to identify variants implicated in disease, we tested whether the PSEN1, p.E318G is associated with AD risk, tau/Aβ pathology or rate of cognitive decline in an APOE dependent manner." (PMID 23990795, 2013). "PSEN1 p.S357*, was reported in a single patient with cerebral amyloid angiopathy and cognitive decline." (PMID 40909785, 2025). "Although pathogenic variants in PSEN1 leading to autosomal‐dominant Alzheimer disease (ADAD) are highly penetrant, substantial interindividual variability in the rates of cognitive decline and biomarker change are observed in ADAD." (PMID 37291760, 2023). "Our findings suggest that within PSEN1 E280A carriers, age-related cognitive decline begins earlier in those who are APOE e4+ than for those with other APOE genotypes, including those who are homozygous e3 and e2+." (PMID 37612284, 2023). "LOF mechanism is proposed for PSEN1 and PSEN2 mutations in AD, showing that total PSEN1 and PSEN2 LOF in mouse brain caused progressive cognitive decline and neurodegeneration." (PMID 33853652, 2021).
cognitive decline (continued). "Rare mutations in APP, PSEN1, and PSEN2 cause ADAD; however, the mechanisms by which altered APP processing leads to changes in tau and cognitive decline remain poorly understood." (PMID 30045758, 2018). "Indeed, a general overexpression of Prnp and App in 3- and 6-month-old APP/PSEN1-Tg mutant mice could also contribute to cognitive decline, since previous studies found alterations of these proteins in cortical areas and peripheral blood of MD." (PMID 33795014, 2021). "Among the rest of the gene variants studied, neither the APOE ε7 allele nor the PSEN-1 Glu318Gly mutation were directly associated with SCD and longitudinal cognitive decline, even though these were found only in the SMC groups." (PMID 38534745, 2024). "Haploinsufficiency was also possible with PSEN1 Trp294Ter in a patient with retinitis pigmentosa and acute encephalopathy, PSEN1 Ser357Ter in a patient with cognitive decline and cerebral amyloid angiopathy (CAA), and PSEN1 Gly378fs in a Moroccan family with AD." (PMID 39596030, 2024). "Several studies have investigated the AoO and cognitive decline associated with the APOEε4 status in LOAD; however, the implication of APOEε4 with or without pathogenic variants of PSEN1 in EOAD has not been widely studied." (PMID 37958671, 2023). "Interestingly, exosomes derived from hypoxia-preconditioned MSCs can rescue synaptic dysfunction and cognitive decline in an animal model of early-onset AD (APP/PS1 mice, which are double transgenic mice expressing a chimeric mouse/human APP, and a mutant human presenilin 1, PS1)." (PMID 31906013, 2019).